CAST (calpastatin)
Diseases named in the same sentence as CAST in open-access papers (continued):
Sharing a sentence is not in itself a finding about the gene and the disease.
injury (3 papers, 2017 to 2023). Damage inflicted on the body as the direct or indirect result of an external force, with or without disruption of structural continuity. "129S1/SvlmJ and WSB/EiJ were less responsive, whereas CAST/EiJ was again resistant to changes in transcript levels induced by FA kidney injury." (PMID 36752209, 2023). "To evaluate whether CAST overexpression would allow for a better and/or faster recovery after brain injury, we performed several cognitive behavioral tests on WT and hCAST mice, on the 3rd (short-term) or 8th (long-term) week after treatment with either KA or SAL." (PMID 28386216, 2017).
ovarian carcinoma (3 papers, 2012 to 2019). A malignant neoplasm originating from the surface ovarian epithelium. "Yet very little information is available regarding the association of calpains and calpastatin expression with clinicopathological factors and prognosis in ovarian cancer." (PMID 30448882, 2019). "In conclusion, both the previous and the current ovarian cancer patient-based studies indicate that calpain-2 expression is adversely associated with overall survival, with calpain-4 and calpastatin expression also negatively associated with overall survival in the current study." (PMID 30448882, 2019). "Calpain and calpastatin expression varied among ovarian cancer cell lines yet their expression levels were similar between chemo-sensitive cells and resistant counterparts." (PMID 30448882, 2019). "Calpain-1, calpain-2, calpain-4 and calpastatin expression were evaluated in primary ovarian carcinomas (n = 575) by immunohistochemistry." (PMID 30448882, 2019). "The conventional calpains and calpastatin have been confirmed to play an important role in ovarian cancer; however, the precise mechanisms whereby they exert effects remain to be elucidated." (PMID 30448882, 2019). "Calpains and calpastatin showed predominant granular/diffuse staining in the cytoplasm of the ovarian cancer cells with heterogeneity between adjacent tumour cells, varying from weak to intense staining." (PMID 30448882, 2019). "Tissue expression of calpastatin, calpain-1 and calpain-2 was assessed in a series of 154 ovarian cancer patients treated with platinum-based chemotherapy." (PMID 22435971, 2012). "The expression of calpain-1, calpain-2 and calpastatin were determined using standard immunohistochemistry on a tissue microarray of 154 primary ovarian carcinomas from patients subsequently treated with platinum-based adjuvant chemotherapy." (PMID 22435971, 2012). "The expression levels of calpastatin, calpain-1 and calpain-2 were determined in a cohort of 154 ovarian cancer patients treated with platinum-based adjuvant chemotherapy." (PMID 22435971, 2012). "No prior studies have investigated the expression of calpastatin, calpain-1 and calpain-2 in ovarian cancer, or have tested their association with response to platinum-based chemotherapy in tissue samples." (PMID 22435971, 2012).
psoriasis (3 papers, 2011 to 2025). An autoimmune condition characterized by red, well-delineated plaques with silvery scales that are usually on the extensor surfaces and scalp. "Concerning miRNAs, it has been identified that hsa-miR-19a-3p has great potential to become a biomarker for psoriasis because it binds to the mRNA of seven genes (CAST, TSC1, SPATA2, ERAP1, TNIP1, ERBB3 and SDC4) thatare associated with psoriasis." (PMID 40725409, 2025). "Rs27524-G (CAST/ERAP1 locus) was associated with “ankylosing spondylitis” (OR = 0.84, p = 5.4 × 10−7), “iridocyclitis” (OR = 0.88, p = 6.9 × 10−8) and “psoriasis” (OR = 0.85, p = 1.6 × 10−6)." (PMID 39006426, 2024). "In particular, we and others have documented the presence of anti-calpastatin (a natural specific inhibitor of calpain) antibodies in RA and psoriasis." (PMID 22046434, 2011). "In addition, autoantibodies against calpastatin, a natural and specific inhibitor of calpain, are widely observed in RA and psoriasis patients, and positivity for anti-calpastatin antibodies is known to correlate with serological markers of the disease activity." (PMID 22046434, 2011).
tauopathy (3 papers, 2023 to 2025). Neurodegenerative disorders involving deposition of abnormal tau protein isoforms (tau proteins) in neurons and glial cells in the brain. "Additionally, this differential susceptibility of PWK and CAST mice to tauopathy implicates them as promising founder strains in future genetic mapping studies." (PMID 37606887, 2023).
type 2 diabetes (3 papers, 2014 to 2022). "In mouse models of type-1 and type-2 diabetes, transgenic over-expression of calpastatin reduces vascular ROS production, inhibits peroxynitrite formation, and attenuates the dysfunction of endothelium-dependent relaxation." (PMID 24886224, 2014). "Similarly, the protective effect of calpastatin over-expression on endothelial function was also observed in a mouse model of type-2 diabetes, db/db mice (data not shown)." (PMID 24886224, 2014).
amyotrophic lateral sclerosis (2 papers, 2021 to 2023). Amyotrophic lateral sclerosis (ALS) is a neurodegenerative disease characterized by progressive muscular paralysis reflecting degeneration of motor neurons in the primary motor cortex, corticospinal tracts, brainstem and spinal cord. "In an Amyotrophic Lateral Sclerosis mouse model, higher CAST expression was associated with neuroprotective effects." (PMID 36855067, 2023).
COVID-19 (2 papers, 2023 to 2024). A disease caused by infection with severe acute respiratory syndrome coronavirus 2. "In particular, our findings highlight the utility of CAST mice as a model for severe COVID-19 that leads to lethality without associated encephalitis." (PMID 39149485, 2024).
diabetes (2 papers, 2014 to 2022). "Concurrent beta cell-specific overexpression of human calpastatin (CAST) (hIAPP:hCAST), which inhibits calpain, delays or prevents diabetes in hIAPP transgenic mice." (PMID 34554282, 2022). "Taken together, over-expression of calpastatin reduces endothelium-dependent dysfunction in diabetes." (PMID 24886224, 2014). "In parallel, diabetes-induced reduction of endothelium-dependent relaxation in aortic ring was reversed by over-expression of calpastatin in mouse models of diabetes." (PMID 24886224, 2014). "To investigate whether the functional improvement by calpain inhibition was mediated through eNOS-derived NO pathway, we induced diabetes in eNOS-KO and eNOS-KO/Tg-CAST mice by STZ injection." (PMID 24886224, 2014).
encephalitis (2 papers, 2023 to 2024). An acute inflammatory process affecting the brain parenchyma. "However, pathology in the CNS of CAST x K18-hACE2 was striking in that microthrombi were evident in capillaries with extensive hemorrhage in the absence of encephalitis." (PMID 37491352, 2023).
essential hypertension (2 papers, 2002 to 2012). Hypertension that presents without an identifiable cause. "In a previous work, two of us (E.L. and L.B.)showed –using the same transgenic mice– that calpastatin overexpression limits hypertension-induced intimal fibrosis in blood vessels via a decrease in inflammatory cell recruitment and secretion of MIP-1." (PMID 22615899, 2012). "It has been reported that the equilibrium between the erythrocyte protease calpain I and its physiological inhibitor calpastatin is disrupted in patients with essential hypertension." (PMID 11836545, 2002). "Protective factors provided by calpastatin against calpain I activity may be diminished in hypertension, which could explain why it has been reported that calpastatin concentration is decreased." (PMID 11836545, 2002). "The protective factor provided by calpastatin against calpain I activity may diminish under hypertension." (PMID 11836545, 2002).
fetal growth restriction (2 papers, 2021 to 2025). A fetus that does not grow beyond the 10th percentile of conventionally accepted weight for gestational age. "While results of desmin and troponin T degradation did not support increased toughness of IUHS loin muscles would owe to differential proteolysis, there is some evidence to suggest intrauterine growth restriction can increase shear force through upregulation of calpastatin." (PMID 33800814, 2021).
Guillain-Barre syndrome (2 papers, 2022). A spectrum of rare post-infectious neuropathies that usually occur in otherwise healthy patients. "Our results suggest that the calpain-calpastatin system could be involved in a wide variety of demyelinating diseases in the PNS, such as CMT1E, the demyelinating form of Guillain-Barré syndrome, and neuropathic pain, among others." (PMID 36499770, 2022).
heart failure (2 papers, 2016 to 2023). Inability of the heart to pump blood at an adequate rate to meet tissue metabolic requirements. "The calpastatin-calpain system has been extensively implicated in cardiac remodeling and heart failure and has been proposed as a potential therapeutic target for heart disease." (PMID 27588447, 2016).
infarction (2 papers, 2015 to 2022). A localised pathological necrosis of tissue resulting from obstruction of the blood supply usually by a thrombus, an embolus, or vascular torsion. "In the present study, we established a transgenic mouse model overexpressing human CAST and provided the experimental evidence that post-infarction myocardial remodeling is associated with up-regulation and activation of calpains and down-regulation of CAST." (PMID 25786109, 2015). "In mice, the restriction of calpain-1 and calpain-2 activities by using a cardiomyocyte-specific deletion of the common subunit Capn4 or by overexpressing calpastatin reduced adverse-post-infarction remodeling and mortality." (PMID 35456920, 2022). "Transgenic over-expression of CAST inhibits calpain activation and attenuates post-infarction myocardial remodeling." (PMID 25786109, 2015). "The present study aimed to investigate the effect of transgenic over-expression of CAST on the post-infarction myocardial remodeling process." (PMID 25786109, 2015). "Transgenic over-expression of CAST significantly attenuated MI-induced calpains upregulation and activation and blunted post-infarction myocardial remodeling." (PMID 25786109, 2015). "Collectively, the present study indicates that over-expression of CAST attenuates MI-induced activation of calpains and subsequently ameliorates post-infarction myocardial remodeling." (PMID 25786109, 2015). "In addition to post-infarction remodeling, the suppression of Capn4 or the constitutive overexpression of calpastatin attenuated cardiomyocyte hypertrophy and cardiac dysfunction induced by chronic angiotensin II treatment." (PMID 35456920, 2022). "However, the role of CAST over-expression in post-infarction myocardial remodeling remains poorly understood." (PMID 25786109, 2015). "The present study also suggests that overexpression of CAST via vector delivery system may be a therapeutic strategy for post-infarction remodeling." (PMID 25786109, 2015). "Therefore, the present study established transgenic mice ubiquitously over-expressing CAST and used cultured an in vivo model of MI to investigate the role of CAST over-expression in post-infarction myocardial remodeling." (PMID 25786109, 2015).
influenza (2 papers, 2016 to 2021). An acute viral infection of the respiratory tract, occurring in isolated cases, in epidemics, or in pandemics; it is caused by serologically different strains of viruses (influenzaviruses) designated A, B, and C, has a 3-day incubation period, and usually lasts for 3 to 10 days. "CAST is uniquely susceptible to infections such as influenza H3N2 and monkeypox virus." (PMID 33567283, 2021). "Thus, we hypothesized that CAST/EiJ may exhibit a specific deficiency in their response to influenza infection." (PMID 26921172, 2016). "Seven genes were specifically not up-regulated in CAST/EiJ after infection which have not been described in the context of the host response to influenza infections, but may be also important host factors for virus defense in humans." (PMID 26921172, 2016).
kidney damage (2 papers, 2016 to 2022). "To identify putative sequence variants that may account for differential susceptibility to nephropathy, we compared the Sub-IV locus sequence between CAST/EiJ and FVB/NJ strains (Genome Build 38.p3)." (PMID 27736906, 2016).
lymphoma (2 papers, 2009 to 2017). A malignant (clonal) proliferation of B- lymphocytes or T- lymphocytes which involves the lymph nodes, bone marrow and/or extranodal sites. "To examine non-telomerase mechanisms for telomere maintenance in mammalian cells, we used primary cells and lymphomas from telomerase-deficient mice (mTR−/− and Eμmyc+mTR−/−) and CAST/EiJ mouse embryonic fibroblast cells." (PMID 19180191, 2009). "We found that late passage CAST/EiJ mouse embryonic fibroblasts (MEFs) and Eμmyc+mTR−/− lymphomas with short telomeres, exhibit telomere maintenance with minimal changes to the overall length distribution." (PMID 19180191, 2009).
melanoma (2 papers, 2013 to 2020). A malignant, usually aggressive tumor composed of atypical, neoplastic melanocytes. "Since specificity of available calpain inhibitors remains questionable, we compared melanoma progression in wild type (WT) mice and transgenic mice overexpressing calpastatin (CalpTG), which specifically inhibits both conventional isoforms." (PMID 23565252, 2013). "Surprisingly, calpastatin transgene increased melanoma cell migration properties, as evaluated in monolayer repair assay (p = 0.026 at 10 h, n = 6 experiments)." (PMID 23565252, 2013). "To determine the respective importance of each target, we then overexpressed calpastatin in tumor or host in isolation, by using a melanoma cell line from the same C57BL/6 genetic background than tumor bearing mice." (PMID 23565252, 2013). "Collectively, these data suggest that calpain inhibition by calpastatin overexpression limits melanoma growth, vascularization, and immune cell infiltrate but paradoxically amplifies its dissemination to regional lymph nodes." (PMID 23565252, 2013). "Our results highlight some of the mechanisms by which the calpain/calpastatin system controls melanoma growth and metastatic dissemination." (PMID 23565252, 2013). "To assess whether calpastatin transgene in melanoma cells affects apoptosis, we measured propidium iodide-annexin V staining by flow cytometry." (PMID 23565252, 2013). "Transfected melanoma cells (Calpast-Mel) expressed the rabbit calpastatin transgene." (PMID 23565252, 2013). "Since calpain inhibition restricted to melanoma cells limits tumor growth but also increase melanoma cell resistance to apoptosis and dissemination toward lymph nodes, we analyzed the effect of calpastatin transgene expression in melanoma cells on mice survival." (PMID 23565252, 2013). "High IRAK-M expression drastically decreased TRAF6 and calpastatin proteins in melanoma cells but did not change the levels in melanocytes." (PMID 32533049, 2020). "Because calpain activity is regulated through its interaction with calpastatin and not necessarily due to changes in protein levels, we investigated calpain activity from transfected melanoma cells and found that IRAK-M expression increased calpain activity." (PMID 32533049, 2020). "However, restoring calpastatin levels prevented IRAK-M–mediated activation of Bax in Malme-3M and SK-MEL-28 melanomas and substantially reduced cleaved Bax levels in C32 cells." (PMID 32533049, 2020).
myocardial infarction (2 papers, 2015 to 2025). Gross necrosis of the myocardium, as a result of interruption of the blood supply to the area, as in coronary thrombosis. "Calpain is activated following myocardial infarction and ablation of calpastatin (CAST), an endogenous inhibitor of calpains, promotes left ventricular remodeling after myocardial infarction (MI)." (PMID 25786109, 2015).
myocardial ischemia (2 papers, 2022 to 2023). A disorder of cardiac function caused by insufficient blood flow to the muscle tissue of the heart. "Calpain inhibition by genetic deletion of Capn4 or calpastatin overexpression prevents the nuclear translocation of the p65 NF-κB subunit and attenuates hypertrophy induced by myocardial ischemia and angiotensin II." (PMID 35456920, 2022). "Transgenic mouse models with an altered calpain/calpastatin system and the use of calpain inhibitors consistently show that calpains play a key or contributory role in the pathology of a variety of cardiac disorders, including platelet aggregation, myocardial ischemia, and HF." (PMID 35456920, 2022).
myocarditis (2 papers, 2022). Myocarditis is a condition that is characterized by inflammation of the heart muscle (myocardium). "To further uncover the mechanism underlying the effects of calpain in CVB3-induced myocarditis, we induced myocarditis in Tg-CAST mice overexpressing the calpain inhibitor calpastatin and their WT littermates by CVB3 injection." (PMID 35997820, 2022).
pancreatic cancer (2 papers, 2012 to 2022). "In summary, this study demonstrates that low expression of calpain-2 is associated with poor survival in pancreatic cancer and low cytoplasmic calpastatin expression is associated with poor survival in cancers of the bile duct and ampulla." (PMID 23140395, 2012). "The results suggest that calpain-2 and calpastatin expression is important in pancreatic cancers, influencing disease progression." (PMID 23140395, 2012). "This study examined the expression of calpain-1 (μ-calpain catalytic subunit), calpain-2 (m-calpain subunit) and calpastatin in cancers of the pancreas, bile duct and ampulla using immunohistochemistry." (PMID 23140395, 2012). "Based on the HPA database, immunohistochemistry suggested that CAST, CCDC6, and ERLIN1 protein expression was lower in normal pancreatic tissues but higher in pancreatic cancer tissues." (PMID 35938160, 2022). "The expression of μ-calpain, m-calpain and calpastatin has not been previously examined in pancreatic, ampullary or bile duct cancers, however, a single nucleotide polymorphism of calpain-10 (CAPN10) has been associated with an increased risk of developing pancreatic cancer in smokers." (PMID 23140395, 2012).
PLACK syndrome (2 papers, 2021 to 2025). "The diagnosis of PLACK syndrome was confirmed by detecting a novel homozygous frameshifting variant in CAST in the affected children." (PMID 41300744, 2025). "Previously reported variants in CAST associated with PLACK syndrome have been truncating in nature (frameshift, splice-site, and nonsense mutations)." (PMID 41300744, 2025). "Recently, dilated cardiomyopathy (DCM) has emerged as a potential systemic manifestation of PLACK syndrome, raising concerns about the impact of CAST deficiency on myocardial function." (PMID 41300744, 2025). "In this study, we describe five children in three sibships of an extended consanguineous family with PLACK syndrome caused by a novel homozygous frameshift variant in CAST." (PMID 41300744, 2025). "One case previously reported as recessive PC has now been identified as PLACK syndrome with a mutation in the CAST gene." (PMID 34724947, 2021). "PLACK syndrome, caused by biallelic loss-of-function (LOF) variants in the CAST gene, is an ultra-rare autosomal recessive disorder characterized by the following defining dermatologic features: peeling skin, leukonychia, acral punctate keratoses, cheilitis, and knuckle pads (PLACK)." (PMID 41300744, 2025).